DAB2 (DAB adaptor protein 2)
Diseases named in the same sentence as DAB2 in open-access papers (continued):
Sharing a sentence is not in itself a finding about the gene and the disease.
cancer (continued). "A recent strong interest in microRNAs (miRNA) in cancer has identified DAB2 as a common target." (PMID 36614139, 2022). "ARH is highly expressed in keratinocytes compared to the human cancer cell lines, where Dab2 and Numb might play a more prominent role in regulating the subcellular distribution of β5." (PMID 35532004, 2022). "It was reported that miR-106b may stimulate cancer cell growth through targeting DAB2, FUT6, MYC, and multiple mechanisms." (PMID 34519258, 2021). "The epigenetic silencing of DAB2 has been investigated in other human cancers." (PMID 33945993, 2021). "These diversities among cancer types and cell lines may be correlated with the tissue-specific differentially expression patterns of DAB2." (PMID 31968685, 2020). "Additionally, the induction of DAB2 expression reduced cancer growth, migration, and invasion 21-25, 27-31." (PMID 32025216, 2020). "The predominant locations of DAB2 expression were in the cytoplasm of cancer and stromal cells." (PMID 31968685, 2020). "DAB2 has low expression in many human cancers and was regulated by TGF-β1 in previous studies." (PMID 26769181, 2016). "Low-DAB2 cancer cells, validated by DAB2 knockdown or over-expression, had higher phosphorylated ERK and migration abilities, which could be suppressed by ERK inhibitor treatment." (PMID 27036032, 2016). "It interacts directly with DAB2, which suppresses the growth of many cancer types." (PMID 26587829, 2015). "The objective of this study was to systematically review expressions of Dab2 in human cancers." (PMID 24772157, 2014). "Although Dab2 promoter hyper-methylation have been observed in some cancer cells, there are still few reasons to attribute down-regulated expression of Dab2 to the promoter hypermethylation unless further credible evidences emerge from other cancer cells (P = 0.19)." (PMID 24772157, 2014). "This is the first study demonstrating frequent DAB2 promoter hypermethylation in human cancer." (PMID 20525238, 2010). "Therefore, the downregulation of MAF, GATA6, and DAB2 may be associated with dysregulated proteasomal function, resulting in EMT and the immune escape of cancer cells." (PMID 37779141, 2023). "Additionally, some studies have shown that loss of DAB2 expression is not consistent amongst all subtypes of a particular cancer type." (PMID 36614139, 2022). "Furthermore, our in vitro study showed that DAB2 expression of fibroblasts in stromal lesions may affect the promotion of EMT in cancer cells." (PMID 31968685, 2020). "Furthermore, differentially hydroxymethylated genes within this pathway, including the PCa-inhibitory genes secreted fizzled-related protein 1 (SFRP1) and Dab, mitogen-responsive phosphoprotein homolog 2 (DAB2), exhibited significantly lower expression in cancer than in the normal cell line." (PMID 26981160, 2016). "Subsequent quantitative reverse transcription PCR and immunoblot analysis at a subset of cancer cell lines, such as DMS114 or K562 cells, induced transcription as well as protein expression levels of DAB2 in RepID-depleted conditions." (PMID 37461562, 2023). "As the OSE layer becomes dysplastic and progresses into cancer, the OSE becomes DAB2- and Ki67+17,21." (PMID 29196616, 2017). "Reduction of GATA6 and Dab2 expression in HIO and cancer lines is more apparent by real-time RT-PCR." (PMID 19649254, 2009). "We focused on ENPEP, TIMP1, CD36, MARCKS, DAB2, CXCL14, miR-181b-5p, and miR-222-3p—genes and miRNAs previously implicated in cancer but not comprehensively analyzed in the context of EVs in BC." (PMID 40565366, 2025). "The relationship between DAB2 expression and promoter methylation was not consistent for all cancer types." (PMID 36614139, 2022). "Together, these results suggest that downregulation of Dab2 may trigger an EMT phenotype concomitant with increased expression of cell surface markers and pluripotency factors that are indicative of the cancer stem cell phenotype." (PMID 31101868, 2019).
cancer (continued). "Results of the Pearson χ2 test revealed that abnormal expression of Dab2 was not significant correlated with the types of cancers from which cancer cell lines originated (χ2 = 3.23, P = 0.36)." (PMID 24772157, 2014). "The ratio of Dab2 promotor hypermethylation is 34.54% in cancer tissues which Dab2 expression are lost, but none in the control tissues or cells by Methylation-specific PCR (MSP)." (PMID 24772157, 2014). "Four genes (DAB2, DCN, CELF2 and COL1A2) have appeared previously in cancers." (PMID 22867264, 2012). "Although decrease or absent of DAB2 has been reported in several cancer types, the status in NPC has not been explored." (PMID 20525238, 2010). "Furthermore, new standards must be ruled out for the evaluation of Dab2 expression in cancer cell lines in the near future." (PMID 24772157, 2014). "DAB2 and CCNE1 are a tumor suppressor gene and oncogene pair normally involved in strong stabilizing molecular interaction negative feedback loops, and it is these interactions that are sufficiently perturbed during cancer development." (PMID 30944378, 2019).
infection (4 papers, 2016 to 2024). The state of being infected such as from the introduction of a foreign agent such as serum, vaccine, antigenic substance or organism. "In addition, the upregulation of Disabled homolog 2 (Dab2) may facilitate Treg-mediated immunosuppression in response to infection; a downregulation of this protein has been linked with a pro-inflammatory switch." (PMID 35167594, 2022). "Third, in myoblasts with stable knockdown of Dab2 after lentiviral infection of shRNA (clone 5-2), remarkably fewer myotubes and a lower myogenic fusion index were observed." (PMID 32607799, 2020). "Furthermore, we also confirmed that H pylori promoted DAB2 expression and activation of STAT3 signaling after infection of mice with H pylori PMSS1." (PMID 38481347, 2024).
cardiovascular disease (2 papers, 2020 to 2023). "In this review we focus on the epsin and Dab2 proteins, which play crucial roles in clathrin-mediated endocytosis and are implicated as important modulators of cardiovascular diseases." (PMID 33363178, 2020). "Several endocytic proteins including sorting nexin (SNX), epsins, and disabled homolog 2 (Dab2) play an indispensable role in cardiovascular diseases." (PMID 36769293, 2023). "In this review, we focus on the role of epsins and Dab2 in controlling these sorting processes in the context of cardiovascular disease." (PMID 33363178, 2020).
kidney disease (1 paper, 2021). "This is consistent with earlier publications indicating the role of proximal tubule-specific DAB2 expression in kidney disease development." (PMID 33859189, 2021).
DAB2 also shares sentences with these, for which no sentence is quoted: esophageal squamous cell carcinoma (3 papers); urothelial carcinoma (3); adenocarcinoma (2); metastatic tumor (2); ovarian tumor (2); acute myeloid leukaemia (1); amyotrophic lateral sclerosis (1); Astrocytoma (1); atrophic gastritis (1); carcinoma in situ (1); clear cell renal cell carcinoma (1); cognitive disorder (1); Colon (1); connective tissue disorder (1); cutaneous melanoma (1); endocrine system disorder (1); endothelial dysfunction (1); glioblastoma (1); glioma (1); infectious disease (1); inflammatory bowel disease (1); invasive ductal carcinoma (1); invasive lobular carcinoma (1); liposarcoma (1); liver fibrosis (1); medullary carcinoma (1); melanoma (1); mole (1); mucinous ovarian cancer (1); mucinous ovarian tumors (1).
A further 9 diseases each share a sentence with DAB2 in 1 paper.